BMX (BMX non-receptor tyrosine kinase)
Description:
Non-receptor tyrosine kinase that plays central but diverse modulatory roles in various signaling processes involved in the regulation of actin reorganization, cell migration, cell proliferation and survival, cell adhesion, and apoptosis. Participates in signal transduction stimulated by growth factor receptors, cytokine receptors, G protein-coupled receptors, antigen receptors and integrins. Induces tyrosine phosphorylation of BCAR1 in response to integrin regulation. Activation of BMX by integrins is mediated by PTK2/FAK1, a key mediator of integrin signaling events leading to the regulation of actin cytoskeleton and cell motility. Plays a critical role in TNF-induced angiogenesis, and implicated in the signaling of TEK and FLT1 receptors, 2 important receptor families essential for angiogenesis. Required for the phosphorylation and activation of STAT3, a transcription factor involved in cell differentiation. Also involved in interleukin-6 (IL6) induced differentiation. Also plays a role in programming adaptive cytoprotection against extracellular stress in different cell systems, salivary epithelial cells, brain endothelial cells, and dermal fibroblasts. May be involved in regulation of endocytosis through its interaction with an endosomal protein RUFY1. May also play a role in the growth and differentiation of hematopoietic cells; as well as in signal transduction in endocardial and arterial endothelial cells.
Synonyms: ETK; PSCTK3; PSCTK2
Tractability: Small molecule: an approved drug acts on it; a structure with a bound ligand is known; a high-quality ligand is known; it has a high-quality binding pocket; it belongs to a druggable protein family. Antibody: its Gene Ontology location is reachable by antibodies, with high confidence; the Human Protein Atlas places it where antibodies can reach. PROTAC: ubiquitination databases record sites on it; a small molecule that binds it is known.
Target class: TK protein kinase group; Kinase; Protein Kinase; Enzyme; Tyrosine protein kinase Tec family
Chemical probes: BMX-IN-1 (high quality)
Gene: Protein-coding gene on chromosome X (15,464,246 to 15,556,529, forward strand). Ensembl gene ENSG00000102010.
Subcellular location: Cytoplasm
Subcellular location (Human Protein Atlas): Plasma membrane; Nucleoplasm
Pathways (Reactome):
Metabolism: Synthesis of PIPs at the plasma membrane
Programmed Cell Death: Apoptotic cleavage of cellular proteins
Gene Ontology:
Molecular function: non-membrane spanning protein tyrosine kinase activity; protein binding; protein tyrosine kinase activity; ATP binding; protein kinase activity
Biological process: signal transduction; adaptive immune response; B cell receptor signaling pathway; mesoderm development; phosphatidylinositol biosynthetic process; protein phosphorylation; intracellular signal transduction
Cellular component: plasma membrane; ruffle membrane; cytosol; cytoplasm
Homologues: Orthologues: chimpanzee BMX (99% identical), macaque BMX (94% identical), guinea pig BMX (89% identical), rabbit BMX (89% identical), pig BMX (89% identical), mouse Bmx (88% identical), rat Bmx (87% identical), dog BMX (77% identical). Paralogues in human: BTK (49% identical), TEC (45% identical), ITK (44% identical), TXK (36% identical), ABL2 (26% identical), FRK (25% identical), ABL1 (25% identical), FYN (24% identical), SRC (24% identical), FGR (24% identical), LYN (24% identical), FER (23% identical), and 20 more.
Diseases named in the same sentence as BMX in open-access papers:
BMX is named in the same sentence as 67 diseases in open-access papers, as found by Europe PMC text mining. Sharing a sentence is not in itself a finding about the gene and the disease. The quoted sentences say what the papers report.
prostate carcinoma (13 papers, 2010 to 2025). A carcinoma that arises from epithelial cells of the prostate gland. "We therefore set out to test pharmacological BMX inhibition in our cellular models, using the readily available irreversible BMX inhibitor BMX-IN-1, which has demonstrated efficacy in prostate cancer lines." (PMID 39133652, 2024). "BMX blockade and inhibition of 3βHSD1 phosphorylation impeded expression of androgen-regulated genes and prostate cancer proliferation." (PMID 36647826, 2023). "In conclusion, our findings suggested that the phosphorylation of 3βHSD1 Y344 promoted prostate cancer proliferation, and targeting BMX as its regulatory kinase blocked the growth of prostate cancer cells." (PMID 36647826, 2023). "Most importantly, the authors demonstrated that BMX blockage, either by siRNA or a pharmacologic inhibitor, blocked androgen biosynthesis in prostate cancer cells and cultured patient tissues." (PMID 36647834, 2023). "Inhibition of BMX activity by genetic or pharmacologic approaches blocked androgen biosynthesis in prostate cancer cells and inhibited tumor growth in preclinical xenograft models." (PMID 36647834, 2023). "BMX contributes to the castration resistance in prostate cancer by positively mediating the activities of multiple receptor tyrosine kinases (RTK) through inducing the generation of phosphotyrosine-tyrosine (pYY) phosphorylation in their activation loop." (PMID 31130822, 2019). "Because wild type BMX functions as an oncogene in prostate cancer, we decided to explore the role of BMXΔN in our study of lung carcinogenesis." (PMID 28422715, 2017). "Conversely, knockdown of BMX using short interfering RNA in prostate cancer cells inhibited cell proliferation, and expression of a kinase-inactive mutant BMX in MDA-MB435 breast cancer cells also suppressed cell proliferation and tumorigenicity." (PMID 28514765, 2017). "Overexpression of BMX in androgen-sensitive LNCaP cells promotes tumor growth while knocking down BMX expression in hormone-insensitive prostate cancer cells inhibits tumor growth under androgen-depleted conditions." (PMID 28422715, 2017). "Previous research has shown that BMX can mediate cell proliferation, survival, apoptosis, migration and invasion in various cancers, such as colorectal cancer, breast cancer, prostate cancer and bladder cancer." (PMID 28514765, 2017). "According to earlier research, BMX plays a critical role in several biological processes, such as inflammation, cardiovascular disease, cancer, particularly glioblastoma cancer stem cells, and solid tumors such as breast and prostate cancer." (PMID 39347140, 2024). "Based on these findings, we hypothesized that BMX inhibitors also inhibit prostate cancer proliferative activity." (PMID 36647826, 2023). "In addition, other studies have demonstrated that BMX can promote the progression of prostate cancer and breast cancer." (PMID 36873244, 2023). "To explore whether targeting regulatory kinases can inhibit prostate cancer cell proliferation, we generated LNCaP cells stably expressing shNT or 2 shRNA sequences against BMX." (PMID 36647826, 2023). "BMX expression is upregulated in response to androgen ablation in prostate cancer, suggesting that Etk/BMX may be involved in the development and progression of CRPC." (PMID 36647826, 2023). "Although BMX has a role in the formation of leukemia, our research is the first to demonstrate that BMX may play a significant role in the regulation of prostate cancer invasion and TICs." (PMID 20929579, 2010).
prostate carcinoma (continued). "From a functional standpoint, BMX was shown to modulate chemoresistance of small cell lung cancer cells (SCLC) and promote proliferation of prostate cancer cell lines." (PMID 39133652, 2024). "Second, the induction of antiapoptotic signals by BMX are observed in different cancer types, including BCL2/BCL-xl expression in SCLC, and PIM-1 expression in prostate cancer." (PMID 39133652, 2024). "Further, we tested several BTK/BMX inhibitors, with HPLC analyses showing that zanubrutinib or ibrutinib treatment significantly decreased DHEA metabolism in multiple prostate cancer (LNCaP, C4-2, and VCaP) cell lines." (PMID 36647826, 2023). "It is still intriguing how the 3βHSD1-BMX feed-forward loop is regulated in prostate cancer cells; the precise role of DHEA in activation of BMX remains unclear." (PMID 36647834, 2023). "Although, BMX has been reported in glioblastoma stem cells and various somatic carcinomas, such as prostate cancer, breast cancer and bladder cancer, the function of BMX in cervical carcinoma is still not known." (PMID 28514765, 2017). "BMX overexpression has been reported in a number of cancers, including AML, prostate cancer, non-oncological diseases, skin keratinocytes and upregulated during stress." (PMID 31970440, 2020).
glioblastoma (12 papers, 2016 to 2025). The most malignant astrocytic tumor (WHO grade IV). "Among these genes, BMX caught our attention because of its reported role in maintaining glioblastoma stem cells and the possibility to pharmacologically target its enzymatic function." (PMID 39133652, 2024). "BMX expression is elevated in multiple tumor types, including prostate, cervical, renal, and colorectal carcinoma, as well as glioblastoma." (PMID 39133652, 2024). "Ibrutinib, a BTK inhibitor developed to treat chronic lymphocytic leukemia and small lymphocytic lymphoma, has shown promise in treating aggressive glioblastoma by interacting with BMX." (PMID 37888725, 2023). "Ibrutinib is a BMX inhibitor that crosses the blood-brain barrier and effectively inhibits the activation of glioblastoma stem cells STAT3." (PMID 36923251, 2023). "The unrestricted self-division ability and differentiation characteristics of glioblastoma stem cells are inseparable from BMX-mediated signal transduction." (PMID 36923251, 2023). "Bone marrow kinase on chromosome X (BMX) has been demonstrated to be expressed in several cancers, and to modulate the survival and tumorigenicity of cancer stem cells involved in glioblastoma." (PMID 31130822, 2019). "Previous studies have demonstrated the high expression of BTK/BMX in glioblastoma." (PMID 38589905, 2024). "Importantly, BMX expression was also reported to be essential for the tumor-initiating ability of glioblastoma stem cells." (PMID 39133652, 2024). "In a recent study, the role of BMX-STAT3 in glioblastoma radioresistance was demonstrated, indicating that pharmacological inhibition of BMX-mediated STAT3 activation in combination with radiotherapy effectively suppresses tumor growth in glioblastoma-bearing mice." (PMID 30845764, 2019). "A study has shown that BMX could maintain self-renewal and tumorigenic potential of glioblastoma stem cells by activating STAT3." (PMID 28422715, 2017). "For both spheroid models, serum addition resulted in rapid cell adherence alongside a progressive decrease in BMX expression, consistent with the notion that the expression of this kinase is restricted to a less-differentiated tumor cell phenotype, as previously reported in glioblastoma." (PMID 39133652, 2024). "Moreover, BMX has also been identified as an activator of STAT3 in glioblastoma stem cells." (PMID 28514765, 2017). "BMX (NBM-T-L-BMX-OS01), a histone deacetylase 8 inhibitor (HDAC8i), shows significant anti-cell proliferation effects in CRC cells, human umbilical endothelial cells, lung cancer cells, and glioblastoma cells, and it also exhibits tumor suppression ability in an animal xenograft model." (PMID 36575468, 2022). "Additionally, BMX knockdown could block the STAT3 activation, while inhibiting the glioblastoma stem cell transcription factors to disrupt the tumorigenicity of glioblastoma stem cells." (PMID 31130822, 2019).
glioma (10 papers, 2013 to 2025). A benign or malignant brain and spinal cord tumor that arises from glial cells (astrocytes, oligodendrocytes, ependymal cells). "For example, BMX is considered to be an essential factor for the maintenance of glioma stem cell-derived pericytes, while the inhibition of BMX is known to improve chemotherapeutic efficacy." (PMID 31130822, 2019). "The selective inhibition of BMX (a member of the Tec tyrosine kinase family), significantly expressed in glioma stem cell-derived pericytes, selectively affects the tumor-BBB (but not the BBB), allowing drug effusion into tumors and enhancing the chemotherapeutic efficacy of drugs." (PMID 31861092, 2019). "As a consequence of this, targeting glioma stem cell-derived pericytes through ibrutinib (BMX inhibition, food and drug administration (FDA)-approved) could disrupt the blood tumor barrier but not the normal BBB." (PMID 31861092, 2019). "Mechanistically, BMX bypasses the suppressor of cytokine signaling 3 (SOCS3)-mediated inhibition of JAK2, whereas targeting of the BMX dampens the JAK2-mediated STAT3 activation, underlying a new molecular basis in which to specifically eliminate the glioma stem cells." (PMID 31130822, 2019). "Previous studies have shown high BTK expression on glioma cells and ibrutinib’s efficacy to hinder lymphoma and other solid tumors progression through inhibition of the BTK/BMX pathway." (PMID 38589905, 2024). "In a model of glioma, CD9-enriched EVs derived from endothelial cells also enhance glioma stem cell tumorigenesis by activating the BMX/STAT3 axis." (PMID 33738282, 2021). "Ibrutinib has also been found to inhibit BMX (a non-receptor tyrosine kinase) mediate glioma stem cell (GSC)-derived pericyte growth and also disrupt the blood–tumor barrier, which augmented glioma-specific chemotherapeutic efficacy." (PMID 32455989, 2020).
breast carcinoma (6 papers, 2014 to 2025). "Utilising the MBA-MD-231 breast cancer cell line, which was the most resistant to treatment with BMX inhibitors alone, we determined the cellular IC50 values for each compound." (PMID 41213918, 2025). "In breast cancer BMX overexpression promotes proliferation by upregulating the activity of downstream substrates Protease Activated Receptor 1 (PAR1), p21 Activated kinase 1 (PAK1), and Signal Transducer and Activator of Transcription 1 (STAT1;)." (PMID 41213918, 2025). "Further, BMX inhibition may play a role in blocking estrogen biosynthesis in women with estrogen-driven postmenopausal breast cancer." (PMID 36647826, 2023). "For instance, BMX significantly promoted cell proliferation in human breast cancer MCF-7 cells." (PMID 28514765, 2017). "Furthermore, given that 3βHSD1 is also critical for conversion of extragonadal precursor steroids to estrogen and progesterone, the 3βHSD1/BMX axis may also play a role in other types of cancers, such as breast cancer." (PMID 36647834, 2023).
cardiac hypertrophy (5 papers, 2015 to 2025). "The role of BMX gene silencing is to inhibit downstream STAT3 signaling which is an important cardioprotective factor associated with cardiac hypertrophy." (PMID 35296647, 2022). "STAT3 activation is an important cardioprotective factor associated with cardiac hypertrophy, and the role of BMX gene silencing is to inhibit downstream STAT3 signaling." (PMID 35296647, 2022). "Regarding BMX, highly selective inhibitors should be developed and systematically evaluated in models such as atherosclerosis and myocardial hypertrophy to assess their effects on vascular endothelium and myocardial remodeling." (PMID 41567642, 2025). "In pathological cardiac hypertrophy development, inactivation of BMX abolished Ang II‐induced cardiac hypertrophy in mice." (PMID 31642192, 2020).
hepatocellular carcinoma (4 papers, 2014 to 2018). A malignant tumor that arises from hepatocytes. "The epithelial and endothelial tyrosine kinase/bone marrow tyrosine kinase gene in chromosome X protein (BMX), a member of the Tec (tyrosine kinase expressed in hepatocellular carcinoma) family of non-receptor tyrosine kinases, is present in epithelial, endothelial, and granulomonocytic cells." (PMID 29419747, 2018).
Sepsis (4 papers, 2020 to 2025). Sepsis is defined as life-threatening organ dysfunction caused by a dysregulated host response to infection. "In conclusion, this integrated approach provides profound insights into the molecular mechanisms underlying sepsis, pinpointing BMX, GRB10, and GADD45A as pivotal biomarkers and therapeutic targets." (PMID 40230692, 2025). "Collectively, these features position BMX, GRB10, and GADD45A as potential key contributors to the interplay of hyperinflammation, immunosuppression, and oxidative stress that underlies sepsis progression." (PMID 40230692, 2025). "These efforts aim to incorporate BMX, GRB10, and GADD45A into diagnostic panels and personalized treatment strategies, thereby improving sepsis management and patient outcomes." (PMID 40230692, 2025). "In the present study, we identified 5 lipid metabolism-related hub genes (MAPK14, EPHX2, BMX, FCER1A, and PAFAH2) that have the possibility of diagnostic and therapeutic in patients with sepsis by machine learning analysis." (PMID 37180171, 2023). "BMX has been shown to attenuate endothelial permeability and vascular leakage during sepsis." (PMID 37180171, 2023). "Despite our robust findings, several limitations must be addressed to fully utilize BMX, GRB10, and GADD45A as sepsis biomarkers and therapeutic targets." (PMID 40230692, 2025). "In conclusion, this study leverages integrated transcriptomics and ML approaches to identify BMX, GRB10, and GADD45A as pivotal biomarkers and therapeutic targets in sepsis." (PMID 40230692, 2025). "We examined the expression of BMX, GRB10, and GADD45A in sepsis patients, observing significantly elevated expression in sepsis compared to healthy controls." (PMID 40230692, 2025). "The chord diagram highlighted BMX, GRB10, and GADD45A’s involvement in reactive oxygen species metabolism, a critical pathway in sepsis." (PMID 40230692, 2025). "Integration of the outputs from all five algorithms identified BMX, GRB10, and GADD45A as the core biomarkers for sepsis, reinforcing their reliability for diagnosis." (PMID 40230692, 2025). "GSVA analysis further confirmed the roles of BMX, GRB10, and GADD45A in immune dysregulation during sepsis, highlighting their involvement in immune environment alterations." (PMID 40230692, 2025). "Thus, BMX may play a key role in the pathophysiology of sepsis as a hub gene." (PMID 37180171, 2023). "For instance, the BMX-miR-758-3p-AC079586.1 and GRB10-miR-15a-5p-RP11-483P21.6 axes highlight potential regulatory mechanisms through which non-coding RNAs may influence gene expression and sepsis progression." (PMID 40230692, 2025).
colorectal cancer (3 papers, 2018 to 2024). A primary or metastatic malignant neoplasm that affects the colon or rectum. "Importantly, in the organoid culture system, BMX and HCK upregulations resulted in the formation of multilayered polyp-like buds protruding towards the organoid lumen, mimicking the pathological polyp morphology often observed in colorectal cancer." (PMID 35221332, 2022).
small cell lung carcinoma (3 papers, 2016 to 2023). Small cell lung cancer (SCLC) is a highly aggressive malignant neoplasm, accounting for 10-15% of lung cancer cases, characterized byrapid growth, and early metastasis. "Additionally, EPHA3 has been associated with the regulation of multi-drug resistance in small cell lung cancer via the PI3K/BMX/STAT3 signaling pathway." (PMID 29383146, 2017). "EphA3 upregulation in small-cell lung cancer (SCLC) lowered therapeutic resistance by promoting apoptosis and triggering G0/G1 arrest, which was associated with decreased phosphorylation of the PI3K/BMX/STAT3 signalling." (PMID 36830852, 2023).